SERPINA4 (serpin family A member 4)
Description:
Inhibits human amidolytic and kininogenase activities of tissue kallikrein. Inhibition is achieved by formation of an equimolar, heat- and SDS-stable complex between the inhibitor and the enzyme, and generation of a small C-terminal fragment of the inhibitor due to cleavage at the reactive site by tissue kallikrein.
Synonyms: PI-4; KST; PI4; KAL; KLST; kallistatin
Tractability: Small molecule: a structure with a bound ligand is known. Antibody: its Gene Ontology location is reachable by antibodies, with high confidence; UniProt places it where antibodies can reach, with medium confidence; UniProt predicts a signal peptide or a membrane-spanning region. PROTAC: its protein half-life has been measured.
Gene: Protein-coding gene on chromosome 14 (94,561,390 to 94,570,482, forward strand). Ensembl gene ENSG00000100665.
Subcellular location: Secreted
Subcellular location (Human Protein Atlas): Vesicles; Predicted to be secreted
Pathways (Reactome):
Developmental Biology: Developmental Lineage of Pancreatic Acinar Cells
Hemostasis: Platelet degranulation
Gene Ontology:
Molecular function: protein binding; serine-type endopeptidase inhibitor activity
Cellular component: extracellular exosome; extracellular region; platelet dense granule lumen
Genetic constraint (gnomAD): Loss-of-function variants: 24 observed, 26.69 expected, observed/expected ratio (o/e) 0.9, 90% interval 0.65 to 1.26. The upper end of that interval is the gene's LOEUF score, 1.26, which puts it in group 5 of 6, group 1 being the genes least tolerant of losing a copy. Missense variants: 553 observed, 559.32 expected, observed/expected ratio (o/e) 0.99, 90% interval 0.92 to 1.06. Synonymous variants: 242 observed, 235.12 expected, observed/expected ratio (o/e) 1.03, 90% interval 0.93 to 1.14.
Homologues: Orthologues: chimpanzee SERPINA4 (99% identical), macaque SERPINA4 (96% identical), dog SERPINA4 (71% identical), pig SERPINA4 (59% identical), rat Serpina4 (56% identical), tropical clawed frog serpina1 (40% identical), zebrafish serpina1l (36% identical), zebrafish serpina1 (36% identical). Paralogues in human: SERPINA9 (44% identical), SERPINA3 (43% identical), SERPINA11 (43% identical), SERPINA1 (43% identical), SERPINA7 (42% identical), SERPINA5 (41% identical), SERPINA6 (41% identical), SERPINA12 (30% identical), SERPINB1 (30% identical), SERPINB12 (30% identical), SERPINC1 (29% identical), SERPINB3 (29% identical), and 24 more.
Diseases named in the same sentence as SERPINA4 in open-access papers:
SERPINA4 is named in the same sentence as 35 diseases in open-access papers, as found by Europe PMC text mining. Sharing a sentence is not in itself a finding about the gene and the disease. The quoted sentences say what the papers report.
acute kidney injury (5 papers, 2017 to 2024). Sudden and sustained deterioration of the kidney function characterized by decreased glomerular filtration rate, increased serum creatinine or oliguria. "A single nucleotide polymorphism in the SerpinA4 gene was linked to acute kidney injury in COVID-19 patients." (PMID 38760690, 2024). "Of note, the latest study demonstrated that the rs2093266 and rs1955656 polymorphisms in SerpinA4 and SerpinA5 genes might be risk factors for COVID-19-induced AKI (acute kidney injury)." (PMID 36982532, 2023). "SERPINA4 and SERPINA5, but not BCL2 and SIK3 are associated with acute kidney injury in critically ill patients with septic shock." (PMID 35874763, 2022).
Sepsis (4 papers, 2017 to 2026). Sepsis is defined as life-threatening organ dysfunction caused by a dysregulated host response to infection. "In addition, a decrease of the kallikrein inhibitor kallistatin (SERPINA4), also indicative for cluster 1, was reported to be associated with septic shock and sepsis mortality." (PMID 40898225, 2025).
colorectal cancer (2 papers, 2021 to 2023). A primary or metastatic malignant neoplasm that affects the colon or rectum. "SERPINA4, a prominent anti-angiogenesis factor, plays an important role in tumor growth inhibition, especially in colorectal cancer." (PMID 33920951, 2021). "Sun and collaborators investigated the expression of SERPINA4 and its clinical significance in colorectal cancer (CRC) and concluded that the decrease in SERPINA4 expression is associated with invasion depth, nodal involvement, distant metastasis, tumor stage, and differentiation." (PMID 37628784, 2023).
COVID-19 (2 papers, 2023 to 2024). A disease caused by infection with severe acute respiratory syndrome coronavirus 2. "SerpinA4 (Kallistatin) was lower in our COVID-19 patients, and it protects against vascular oxidative stress and inflammation as well as inhibiting angiogenesis." (PMID 38760690, 2024). "Down-regulation of SerpinA4 was noted in COVID-19 non-survivors, indicating a persistent pro-inflammatory signature." (PMID 38760690, 2024).
endometrial cancer (2 papers, 2024 to 2025). Primary or metastatic malignant neoplasm involving the endometrium (mucous membrane that lines the endometrial cavity). "For plasma proteins, a six-biomarker panel combining SERPINA4, APOA2, TTR, CRP, CLEC3B and APOD predicted advanced stage endometrial cancer with AUC 0.93 (0.85–0.99)." (PMID 38513301, 2024).
Hepatic steatosis (2 papers, 2024 to 2025). Steatosis is a term used to denote lipid accumulation within hepatocytes. "We identified 78 secreted proteins that were positively associated with liver steatosis area, with the top hits including fatty acid binding protein 4 (FABP4), kallistatin (SERPINA4), perlecan (HSPG2); all have known roles in lipid metabolism and driving MASLD progression." (PMID 40250425, 2025). "Furthermore, fed Serpina4−/− rats with a MCD diet for 4 weeks to induce hepatic steatosis and 10 weeks to NASH, respectively." (PMID 38472195, 2024).
Hypertension (2 papers, 2021 to 2024). The presence of chronic increased pressure in the systemic arterial system. "Since the amount of kallistatin protein expressed by the SERPINA4 gene is very low in the brain compared to the liver and kidney, previous studies have mainly focused on in-vitro and animal model studies on endothelial cells, cardiac remodeling, hypertension, and renal disease." (PMID 38383562, 2024).
pancreatic cancer (2 papers, 2018 to 2020). "Another study suggested that circ_0006215 could regulate the expression of SERPINA4 by targeting miR‐278a‐3p in pancreatic cancer cells." (PMID 32697386, 2020). "Although it is unknown whether SERPINA4 mediates the progression of pancreatic cancer, it is an early marker of severity in acute pancreatitis." (PMID 29713252, 2018).
abdominal aortic aneurysm (1 paper, 2025). Enlargement and ballooning of the vessel that supplies arterial blood to the abdomen, pelvis and legs. "In addition, in tissue samples from abdominal aortic aneurysms (AAAs), an altered expression of SERPINA4 has been observed." (PMID 40141310, 2025).
cyst (1 paper, 2021). A sac-like closed membranous structure that may be empty or contain fluid or amorphous material. "Such comparison resulted in 4 upregulated (CP, CEACAM5, DMBT1, and KRT6A) and 8 downregulated (CEL, CPA1, CPB1, ALB, SERPINA4, CA2, CLU, and AMBP) DEGs secreted in cyst fluid of high-risk IPMNs." (PMID 34790815, 2021).
liver dysfunction (1 paper, 2017). "SERPINA4 (Kallistatin) is a multifunctional serpin clade A protein expressed from liver and concentration in serum is the reflection of extent of liver dysfunction." (PMID 29159256, 2017).
lung disease (1 paper, 2017). "In our previous efforts in studying the implication of PON1 in LC, we recently discovered that serum PON1 is a highly significant meta-marker, along with SERPINA4, for the differential diagnosis of LC and lung disease." (PMID 28467805, 2017).
myocardial infarction (1 paper, 2025). Gross necrosis of the myocardium, as a result of interruption of the blood supply to the area, as in coronary thrombosis. "Supporting this clinical observation, gene deficiency of Serpina3c in mice, a homolog of human SERPINA4, aggravates myocardial fibrosis and promotes cardiac fibroblast proliferation after myocardial infarction (MI) via Nr4a1/ENO1/glycolysis pathway." (PMID 41561118, 2025).
tumor (4 papers, 2019 to 2023). "Some studies showed that SERPINA4 has an important effect on the inhibition of tumor growth and angiogenesis." (PMID 37628784, 2023). "After adjustment of the data based on tumor characteristics, several genes (e.g., serpin family A member 4 (SERPINA4) and blocked early in transport 1 homolog (BET1L)) were still associated with better PFS in White patients only." (PMID 33920951, 2021). "In contrast genes involved in development and differentiation (Arid5b, Inmt, Grem2, Gdap10), cell metabolism (Alas1, Gsta1, Thrsp, Fdft1, Elovl6), tumor growth (SerpinA4, Cish, Rpl36), and cell cycle control (PLK3, Myc, HNF6/Onecut1) were downregulated." (PMID 33004985, 2020).
cancer (1 paper, 2024). A tumor composed of atypical neoplastic, often pleomorphic cells that invade other tissues. "Plasma protein levels of 11 proteins, including complement C8A and serpin family A member 4 (SERPINA4) were linked to cancer-associated inflammation, while 4 proteins, including C8A and C4B, distinguished early from advanced CRC stages." (PMID 38911905, 2024).
neurodegenerative disease (1 paper, 2023). A disorder of the central nervous system characterized by gradual and progressive loss of neural tissue and neurologic function. "While these studies highlight differential expression/abundance of SERPINA4, its mechanistic role in ALS and other neurodegenerative diseases is unknown though it does play a role in the inhibition of oxidative stress and inflammation." (PMID 37646115, 2023).
SERPINA4 also shares sentences with these, for which no sentence is quoted: breast carcinoma (3 papers); Obesity (2); acute pancreatitis (1); airway hyperresponsiveness (1); cardiac hypertrophy (1); Crohn disease (1); Dent disease (1); Ehlers-Danlos syndrome (1); inflammatory bowel disease (1); Insulin resistance (1); Lowe syndrome (1); metabolic dysfunction-associated steatotic liver disease (1); minimal change disease (1); ovarian carcinoma (1); pancreatitis (1); Parkinsonism (1); rheumatic carditis (1); Shock (1); ulcerative colitis (1).